RN7SKP210 (RN7SK pseudogene 210)
Gene: Miscellaneous RNA gene on chromosome 22 (39,874,255 to 39,874,515, reverse strand). Ensembl gene ENSG00000238875.
Homologues: Orthologues: chimpanzee 7SK (100% identical), mouse Gm54709 (51% identical), guinea pig 7SK (44% identical). Paralogues in human: 7SK (69% identical), RN7SKP174 (67% identical), RN7SKP187 (67% identical), RN7SKP48 (67% identical), RN7SKP160 (66% identical), RN7SKP185 (66% identical), RN7SKP62 (66% identical), RN7SKP222 (66% identical), RN7SKP227 (66% identical), RN7SKP102 (65% identical), RN7SKP156 (65% identical), RN7SKP170 (65% identical), and 284 more.